CYP2A6 (cytochrome P450 family 2 subfamily A member 6)
Diseases named in the same sentence as CYP2A6 in open-access papers (continued):
Sharing a sentence is not in itself a finding about the gene and the disease.
age (1 paper, 2017). A temporal measurement of the time period elapsed since an identifiable point in the life cycle of an organism. "Our observation of the association of the rs113288603 * T allele with age-related hearing loss symptoms and CYP2A6 expression in cerebellar hemisphere is consistent with and validated by these prior findings." (PMID 28432340, 2017). "Our findings confirm the role of tobacco smoking in age-related hearing loss and suggest that CYP2A6 mediates this association (at least in part) by moderating the long-term effects of nicotine or an ototoxic metabolite in the brain to various degrees depending on the individual." (PMID 28432340, 2017).
age-related hearing loss (1 paper, 2017). "Specifically, the association of CYP2A6 rs113288603 with age-related hearing loss observed in nicotine-exposed individuals is mediated by the involvement of CYP2A6 in nicotine metabolism (not by the limited effect on smoking quantity observed)." (PMID 28432340, 2017).
alcohol dependence (1 paper, 2014). Physical and psychological dependence on alcohol. "Among these are genes encoding for the enzymes involved with drug metabolism such as alcohol and aldehyde dehydrogenases, which offer protection against alcoholism and CYP2A6, which offers protections against nicotine addiction." (PMID 25077169, 2014).
arteriosclerosis (1 paper, 2021). A vascular disorder characterized by thickening and hardening of the walls of the arteries. "Wild-type CYP2A6 was recently reported to be a risk index of arteriosclerosis as a lifestyle-related disease in the general Japanese population, although the mechanism is unknown." (PMID 34193316, 2021).
bladder tumors (1 paper, 2016). "Although only one of eight cell lines showed more than one copy increase of the CYP2A6 gene, CYP2A6 amplification was detected in six out of 18 primary bladder tumors where it was associated with the invasive phenotype." (PMID 27902773, 2016). "However, the CYP2A6 gene was amplified in six out of 18 cases of resected primary bladder tumors, suggesting an association with the early stage of cancer invasion." (PMID 27902773, 2016). "Immunohistochemical analyses of 118 primary bladder tumors revealed that CYP2A6 protein expression was also higher in invasive tumors, especially in those of the scattered type." (PMID 27902773, 2016). "This notion was confirmed by significant upregulation of the CYP2A6 protein in invasive bladder tumors, especially in scattered lesions." (PMID 27902773, 2016).
breast tumor (1 paper, 2017). "The differential expression pattern of this gene is similar to that of CYP2A6, wherein the mean normalized expression values in adjacent normal tissue, all BRCA tissue, CA, AS, and AA breast tumor tissues are 0.63, 30.8, 28.6, 1.80, and 24.9, respectively." (PMID 28684774, 2017). "The mean expression values in RPM of CYP2A6 in adjacent normal tissue, all BRCA tissue, CA, AS, and AA breast tumor tissues are 5.63, 75.7, 96.3, 4.89, and 37.0, respectively." (PMID 28684774, 2017).
coronary artery disease (1 paper, 2022). "Sixty-four male active smokers at the age of ≥45 years, diagnosed with coronary artery disease (CAD), were recruited and asked to smoke the usual number of cigarettes in the last 1 month prior to blood collection for CYP2A6 genotyping." (PMID 36123879, 2022).
coronary atherosclerosis (1 paper, 2022). Atherosclerosis of the coronary vasculature. "CYP2A6 gene polymorphism has a significant correlation with the severity of coronary atherosclerosis in male smokers, where the mutant CYP2A6 independently increased the risk of having severe coronary stenosis." (PMID 36123879, 2022). "This study aimed to investigate the correlation between the CYP2A6 gene variants and coronary atherosclerosis severity in Indonesian male smokers." (PMID 36123879, 2022). "We aimed to investigate the correlation between the CYP2A6 gene with the severity of coronary atherosclerosis." (PMID 36123879, 2022). "Firstly, the natural design of this cross-sectional study encouraged us to measure all variables at the same point of time, and thus, whether the severity of coronary atherosclerosis was solely attributable to the CYP2A6 mutant or together with the prolonged nicotine exposure, remains unclear." (PMID 36123879, 2022).
coronary stenosis (1 paper, 2022). Narrowing of the coronary artery lumen diameter. "Mutant CYP2A6 allele, either homozygote or heterozygote, was predominantly contributed to an increased risk of severe coronary artery stenosis compared to the WT." (PMID 36123879, 2022). "Our results showed that all participants with CYP2A6 variants had a significant correlation with severe coronary artery stenosis (P = .006)." (PMID 36123879, 2022). "This suggests that the mutant CYP2A6 gene allele independently increased the risk of severe coronary stenosis with RR 1.15 (95% CI 1.07–1.29, P = .006), compared with WT allele." (PMID 36123879, 2022). "Correlation between CYP2A6 mutant gene with the severity of coronary stenosis, adjusted for cardiovascular risk factors." (PMID 36123879, 2022). "From our analysis, the mutant CYP2A6 gene allele significantly increased the risk 1.2 times higher to have severe coronary stenosis compared to the WT." (PMID 36123879, 2022). "Cross-tabulation between CYP2A6 allele variants and coronary artery stenosis degree." (PMID 36123879, 2022). "Thus, this study suggests that the mutant CYP2A6 gene allele significantly increased the risk of having severe coronary stenosis 1.2 times higher compared to the wild type." (PMID 36123879, 2022). "Coronary artery stenosis degree differences between CYP2A6 variants (compared to wildtype)." (PMID 36123879, 2022). "Our study suggests that CYP2A6 gene mutation has an influential role in the severity of coronary artery stenosis, independent of the nicotine level." (PMID 36123879, 2022).
depression (1 paper, 2018). "However, different SNPS of the SLC6A4 gene and other genes such as THSD4, CHRNA, CYP2A6 have also been associated with depression in COPD." (PMID 29927965, 2018).
diabetes mellitus (1 paper, 2023). A metabolic disorder characterized by abnormally high blood sugar levels due to diminished production of insulin or insulin resistance/desensitization. "CYP1A1, HHIP (hedgehog interacting protein), AGTR2, CYP2A6, and PCK1 are involved in growth and development of diabetes mellitus." (PMID 38137330, 2023).
dry mouth (1 paper, 2017). "Pilocarpine, used in the treatment of glaucoma and dry mouth (xerostomia), is primarily metabolized by CYP2A6 to 3-hydroxypilocarpine." (PMID 29194389, 2017).
esophageal cancer (1 paper, 2024). A primary or metastatic malignant neoplasm involving the esophagus. "In Japan (a population with esophageal squamous cell carcinoma as the predominant form of esophageal cancer, with smoking and alcohol use as risk factors), genomic analysis determined germline polymorphisms in ALDH2 and CYP2A6, which affect alcohol and tobacco metabolism." (PMID 39859964, 2024).
glioblastoma (1 paper, 2021). The most malignant astrocytic tumor (WHO grade IV).
hearing loss (1 paper, 2017). "In the discovery PheWAS in the WHI nicotine-exposed sample, we observed a significant association between CYP2A6 rs113288603 and hearing loss." (PMID 28432340, 2017). "We observed that rs113288603 * T (protective with respect to hearing loss) is significantly associated with increased CYP2A6 expression in cerebellar hemisphere (p = 9.9 × 10−4)." (PMID 28432340, 2017). "We identified a significant association between CYP2A6 rs113288603 and hearing loss symptoms (p = 5.75 × 10−5)." (PMID 28432340, 2017). "Our current PheWAS for CYP2A6 alleles identified association with hearing loss symptoms in nicotine-exposed elderly subjects." (PMID 28432340, 2017). "Rs56113850 and rs12461964 seem to provide a minimal contribution to CYP2A6 brain regulation because they appear to be protective with respect to hearing loss symptoms with effect directions opposite with respect to their associations with hepatic expression and serum and urine NMR." (PMID 28432340, 2017). "Considering smoking behaviors, CYP2A6 rs113288603 also showed a nominal association with smoking status (current vs. former smokers): carriers of the rs113288603 * T (protective for hearing loss) allele are less likely to be current smokers than non-carriers (p = 0.047)." (PMID 28432340, 2017).
liver dysfunction (1 paper, 2022). "The authors determined that susceptibility to coumarin-associated liver dysfunction is not genetically determined by polymorphisms in CYP2A6, concluding that the studied polymorphisms are not the primary reason for coumarin hepatotoxicity." (PMID 36558195, 2022).
lymphedema (1 paper, 2018). Excess fluid collection in tissues, causing swelling. "The preliminary identification (phenotyping) of these patients should permit a safer use of the efficacious and cheap coumarin on all the other lymphedema patients with normally functioning CYP2A6 enzyme." (PMID 29382051, 2018). "However, in the light of the previous findings, lymphedema patients with low active CYP2A6 should be identified and not be treated with coumarin, since they would metabolize it via the cytotoxic pathway leading to o-HPA." (PMID 29382051, 2018).
Nephropathy (1 paper, 2004). A nonspecific term referring to disease or damage of the kidneys. "A positive correlation between Cd-linked nephropathy (urinary N-acetyl-β-d-glucosaminidase excretion) and CYP2A6 activity in men (r = 0.39, p = 0.002) and women (r = 0.37, p = 0.001) suggests that Cd induction of hepatic CYP2A6 expression and Cd-linked nephropathy occurred simultaneously." (PMID 15531436, 2004). "We examined the interrelationships between phenotype of hepatic cytochrome P450 2A6 (CYP2A6), nephropathy, and exposure to cadmium and lead in a group of 118 healthy Thai men and women who had never smoked." (PMID 15531436, 2004).
non-alcoholic steatohepatitis (1 paper, 2016). "Importantly, the authors found that activities of CYP1A2 and CYP2C19 decreased whereas metabolic capacities of CYP2A6 and CYP2C9 increased during progression from healthy livers to steatosis and non-alcoholic steatohepatitis (NASH)." (PMID 27754327, 2016).
opisthorchiasis (1 paper, 2018). Infection with flukes of the genus Opisthorchis. "Previous studies reported that the CYP2A6, an isoform of CYP450, was upregulated in opisthorchiasis and opisthorchiasis-associated CCA patients." (PMID 30440021, 2018).
prostate adenocarcinoma (1 paper, 2025). "In a study of prostate adenocarcinoma (PRAD), the expression of CYP2A6, CYP3A5, and CYP4B1 genes was evaluated in prostate tissue using real-time quantitative PCR (RT-qPCR)." (PMID 40723371, 2025).
sarcoma (1 paper, 2021). A usually aggressive malignant neoplasm of the soft tissue or bone. "Interestingly, the G2 subgroup mainly contained the sarcomas with elevated expression of RDH11, RDH8, RDH16, CYP2A6, and ALDH1A2, all of them were strongly or slightly correlated with poor survival." (PMID 35186946, 2021).
Sepsis (1 paper, 2008). Sepsis is defined as life-threatening organ dysfunction caused by a dysregulated host response to infection. "A polymorphism in CYP2A6, a cytochrome P450 enzyme reported to metabolise tegafur to 5-FU, has been demonstrated in a recent report of one patient treated with UFT who developed severe diarrhoea and fatal sepsis." (PMID 18728662, 2008).
skin reaction (1 paper, 2012). "This could be partly explained by recent reports which showed that NVP was metabolically activated to quinone methidine, a toxic reactive metabolite, by CYP3A4, and, to a lesser extent, CYP2D6, CYP2C19, and CYP2A6, and that this reactive metabolite was responsible for NVP-induced skin reactions." (PMID 22957276, 2012).
systemic lupus erythematosus (1 paper, 2025). An autoimmune multi-organ disease typically associated with vasculopathy and autoantibody production. "Additionally, studies on genetic polymorphisms of CYP2A6 and CYP2C8 in the context of CYC metabolism are limited, particularly in patients with systemic lupus erythematosus (SLE)." (PMID 40630120, 2025).
cancer (35 papers, 2002 to 2026). A tumor composed of atypical neoplastic, often pleomorphic cells that invade other tissues. "On the other hand, CYP2A6 deletion associated increase blood cancers in smokers (OR = 2.05, 95%CI: 1.19–3.53, p = 0.01 after adjustment)." (PMID 32131765, 2020). "To this end, we employed consecutive autopsy cases of Japanese elderly registered in the JG-SNP database to determine the association between CYP2A6 deletion and risk of total cancer and major cancer types." (PMID 32131765, 2020). "We studied the association of CYP2A6 (D) and total cancer in different models of dominant (DD + WD: WW), recessive (DD: WD + WW) and additive (WW: WD: DD)." (PMID 32131765, 2020). "Genetic variations of CYP2A6 gene have been widely studied with respect to its association with levels of nicotine metabolites in vivo, nicotine dependence, smoking behavior and cancer susceptibility." (PMID 32131765, 2020). "In this study, we determined the association of CYP2A6 gene deletion genotypes with various cancer risks." (PMID 32131765, 2020). "ALDH2 and CYP2A6 may contribute to cancer risk, underscoring the importance of abstinence from alcohol and smoking in preventive healthcare." (PMID 41680362, 2026). "At present, whether CYP2A6 structural status can function as a biomarker for therapeutic response or cancer risk stratification remains uncertain and should be addressed in future studies." (PMID 41272073, 2025). "Multiple GWAS analyses showed genetic associations between CYP1A2 and CYP2A6 and cancer." (PMID 39457450, 2024). "Since many cancers are tobacco related, we first studied whether CYP2A6 deletion associate with total cancer in our study sample." (PMID 32131765, 2020). "CYP2A6 variants have been studied for tobacco-related cancers such as lung, bladder, esophageal, oral and urothelial cancers." (PMID 32131765, 2020). "First, association of CYP2A6 W/D genotype and total cancer were determined for all subjects." (PMID 32131765, 2020). "When single-cell-level viability was quantified from the multiplexed (i.e., cell count plus viability) screens, it provided information on both the susceptibility and resistance response of cancer cells to druggable target knockdowns such as CYP2A6 and ONECUT2 genes." (PMID 31467349, 2019). "We genotyped CYP2A6 rs1801272 (also known as CYP2A6*2) because this SNP is relatively common (4% in our population), has been well characterized in previous functional studies, and showed controversial associations with cancer and smoking dependence." (PMID 19479063, 2009). "We undertook an association study to determine whether deletion of CYP2A6 gene associates with total cancer and major cancer types employing data of consecutive autopsy cases registered in the Japanese single-nucleotide polymorphisms for geriatric research (JG-SNP) database." (PMID 32131765, 2020). "However, there were some positive signs that CYP2A6 deletion might associate with the presence of independent cancer in sex and smoking dependent manner." (PMID 32131765, 2020). "Utilising the HCC dataset available through the cancer-genome atlas (TCGA-LIHC dataset), we confirmed that high expression of CYP2A6 was associated with significantly greater median survival in HCC." (PMID 34628485, 2022). "The inhibition of CYP2A6 for instance would hinder its role in bioactivation process of prodrug, tegafur, to 5′fluorouracil (5-FU) in cancer treatments." (PMID 36518400, 2022). "The expression of CYP2A6 was significantly downregulated in most cancer types, especially in HCC patients." (PMID 33455085, 2021). "Differences in tegafur metabolism and 5-fluorouracil formation, resulting from variable CYP2A6 activity, can influence treatment outcomes for cancer patients." (PMID 29194389, 2017). "Tegafur is a prodrug, used in the treatment of a variety of cancers, that is metabolized primarily by CYP2A6 to the active metabolite 5-fluorouracil." (PMID 29194389, 2017).
cancer (continued). "In this study, we identified three novel CYP2A7/CYP2A6 hybrids in Japanese patients with cancer." (PMID 41272073, 2025). "Aside from CYP1A2 and CYP2A6, no significant cancer associations were found for the other phase I and phase II enzymes examined in this study." (PMID 39457450, 2024). "When smoker and non-smoker were separately analyzed, CYP2A6 deletion associated with decreased total cancer in female nonsmokers (OR = 0.67, 95%CI: 0.45–0.99, p = 0.041 after adjustment)." (PMID 32131765, 2020). "As for smoker, CYP2A6 deletion did not associate with total cancer, nor independent cancers of gastric, colorectal and lung." (PMID 32131765, 2020). "Only in female nonsmokers, CYP2A6 deletion associated with decreased total cancer (OR = 0.67, 95%CI: 0.45–0.99, p = 0.041 after adjustment)." (PMID 32131765, 2020). "Therefore, our immunohistochemistry experiments were based on the studies that performed CYP2A6 immunohistochemistry in other human cancers." (PMID 27902773, 2016). "For example, expression differences in DMET genes such as CYP3A4, CYP2A6 and GSTA1 may be associated with cancer risks." (PMID 29177108, 2012). "Conversely, some CYP450 enzymes, like CYP1A1, CYP1A2, CYP1B1, CYP2A6, and CYP2E1, have a role in the onset and development of many cancers by converting pro-carcinogenic substrates into carcinogens." (PMID 39062040, 2024). "Also CYP2A6 deletion associated with decreased total cancer in non-smoking female." (PMID 32131765, 2020). "Whether or not CYP2A6*4 associates with cancer is still controversial." (PMID 32131765, 2020). "Fourteen of the mutated genes in this tumor are involved in metabolism (endogenous molecules as well as drugs), small molecule biochemistry, and cancer: AATF, ATF71P, CRIPAK, CROCC, CYP2A6, DOCK5, GPAT2, KRTAP4–9, LSM14A, MUC2, MYO1F, RHOQ, SUFU, and UTRN." (PMID 29259192, 2017). "Overall, our findings suggested that CYP2A6 deletion do not largely affect presence of total cancer." (PMID 32131765, 2020). "CYP2A6 deletion may not largely affect presence of total cancer." (PMID 32131765, 2020). "Because the CYP2A6 locus in the 19q13 region is separated from the SPINT2 and ACTN4 loci by many genes, CYP2A6 amplification in human cancer has not been shown." (PMID 27902773, 2016).